SNORA11B (small nucleolar RNA, H/ACA box 11B)
Gene: Small nucleolar RNA gene on chromosome 14 (91,126,425 to 91,126,553, forward strand). Ensembl gene ENSG00000221102.
Gene Ontology:
Biological process: RNA processing
Cellular component: nucleolus
Homologues: Orthologues: chimpanzee SNORA11B (99% identical), macaque SNORA11B (98% identical). Paralogues in human: SNORA11C (89% identical), SNORA11D (89% identical), SNORA11E (89% identical), SNORA11F (88% identical), SNORA11 (83% identical), SNORA11G (74% identical).